FOXB2 (forkhead box B2)
Description:
Transcription factor.
Synonyms: bA159H20.4; FKH4
Tractability: No criterion of Open Targets' tractability assessment is met for any kind of drug.
Gene: Protein-coding gene on chromosome 9 (77,018,706 to 77,022,372, forward strand). Ensembl gene ENSG00000204612.
Subcellular location: Nucleus
Gene Ontology:
Molecular function: DNA-binding transcription factor activity, RNA polymerase II-specific; RNA polymerase II cis-regulatory region sequence-specific DNA binding; DNA-binding transcription factor activity; sequence-specific DNA binding
Biological process: anatomical structure morphogenesis; cell differentiation; regulation of transcription by RNA polymerase II; regulation of DNA-templated transcription
Cellular component: chromatin; nucleus
Genetic constraint (gnomAD): Loss-of-function variants: 1 observed, 0.35 expected, observed/expected ratio (o/e) 2.86. That is too few expected variants to judge how well the gene tolerates losing a copy. Missense variants: 513 observed, 450.1 expected, observed/expected ratio (o/e) 1.14, 90% interval 1.06 to 1.23. Synonymous variants: 251 observed, 207.04 expected, observed/expected ratio (o/e) 1.21, 90% interval 1.09 to 1.35.
Homologues: Orthologues: chimpanzee FOXB2 (99% identical), macaque FOXB2 (98% identical), dog FOXB2 (93% identical), pig FOXB2 (93% identical), rabbit FOXB2 (91% identical), mouse Foxb2 (91% identical), rat Foxb2 (91% identical), tropical clawed frog foxb2 (51% identical), zebrafish foxb2 (46% identical), Drosophila melanogaster fd96Ca (30% identical), Caenorhabditis elegans lin-31 (28% identical). Paralogues in human: FOXB1 (44% identical), FOXD1 (23% identical), FOXD2 (22% identical), FOXD3 (22% identical), FOXA2 (22% identical), FOXD4L1 (22% identical), FOXA1 (21% identical), FOXE1 (21% identical), FOXC1 (21% identical), FOXC2 (21% identical), FOXD4 (20% identical), FOXD4L5 (20% identical), and 29 more.
Diseases named in the same sentence as FOXB2 in open-access papers:
FOXB2 is named in the same sentence as 6 diseases in open-access papers, as found by Europe PMC text mining. Sharing a sentence is not in itself a finding about the gene and the disease. The quoted sentences say what the papers report.
prostate carcinoma (6 papers, 2021 to 2024). A carcinoma that arises from epithelial cells of the prostate gland. "Accordingly, a FOXB2/WNT7B gene expression signature was associated with poor prognosis in prostate cancer patient data." (PMID 34298659, 2021). "Inhibition of WNT7B signaling was sufficient to block the effect of FOXB2, and loss-of-function of FOXB2 reduced Wnt transcriptional activity in prostate cancer cell lines." (PMID 34298659, 2021). "We have previously shown that FOXB2 controls Wnt pathway activity in prostate cancer cells via WNT7/RECK, suggesting that these and potentially other FOX family members are functionally redundant in the context of Wnt/β-catenin signaling." (PMID 37011861, 2023). "Our group observed that FOXB2, whose expression is normally restricted to the embryonic brain, is re-expressed in aggressive prostate cancer subtypes." (PMID 34298659, 2021). "Almost all of the FOX genes were differentially expressed in prostate cancer, prostate carcinoma, and metastatic prostate cancer, except FOXA3, FOXB2, FOXC2, FOXI2, FOXI3, FOXP4, and FOXR1." (PMID 36292640, 2022).
chronic kidney disease (1 paper, 2022). Impairment of the renal function secondary to chronic kidney damage persisting for three or more months. "AL353637.1 is a pseudogene nearby the gene FOXB2, also belongs to the FOX family of FOXJ1, and contains a variant (rs115747230) associated with chronic kidney disease." (PMID 35565241, 2022).
tumor (2 papers, 2013 to 2023). "Next, we compared the tumor/normal expression ratios with the methylation measured by BSA (FOXB2 and FOXF1) or array (FOXD3)." (PMID 23324568, 2013). "For a subset of nine tumor-normal pairs, the expression of FOXB2, FOXD3, and FOXF1 was determined using real-time reverse-transcription PCR (RT-qPCR)." (PMID 23324568, 2013). "Only two tumors (both BRAF wildtype) had detectable levels of FOXB2 expression, and an additional three samples showed no detectable FOXB2 expression in either tumor or normal tissue." (PMID 23324568, 2013).
FOXB2 also shares sentences with these, for which no sentence is quoted: cancer (1 paper); melanoma (1); metastatic prostate carcinoma (1).